ERBB2 (erb-b2 receptor tyrosine kinase 2)
Diseases named in the same sentence as ERBB2 in open-access papers (continued):
Sharing a sentence is not in itself a finding about the gene and the disease.
cancer (continued). "Small molecule inhibitors or monoclonal antibodies blocking Abl, ErbB2, or EGFR have become the standard of care for these cancers." (PMID 32069833, 2020). "We identified 156 focal amplifications and 69 focal deletions, in well-known oncogenes, such as ERBB2, CCNE1, KRAS, MYC, EGFR, and CDK6, and cancer-related genes such as GATA4, GATA6, CD44 and ZNF217." (PMID 31570735, 2019). "Positive expression of HER2/c-erbB-2 and EGFR proteins in cancer tissue was significant higher than normal gastric tissue and have significant correlation with prognosis." (PMID 33817143, 2019). "All three Pab bound to ErbB-2 with Kd~6–16 nmol/L and inhibited HER2+ cancer cell growth and proliferation up to 40%." (PMID 31140150, 2019). "MMP14, MDM2, ERBB2, SKP2 and PTGS2, which were previously identified as OGs in human cancer, also have higher rate of amplification in mutation data." (PMID 31205821, 2019). "The HER2/c-erbB-2 and EGFR positive expression rate in the cancer tissues were significantly higher than that of normal gastric tissues." (PMID 33817143, 2019). "ERBB2 and ERBB3 genes belong to the epidermal growth factor receptor (EGFR) family, and they had been identified as common driver genes of multiple cancer types by promoting solid tumor growth." (PMID 32038722, 2019). "The phosphorylated residues Y1221/1222 (ERBB2) and Y1289 (ERRB3) are conserved across species, highlighting the evolutionary impact of tyrosine kinase signaling in cancer cells." (PMID 30645971, 2019). "We further analyzed pathways of the predicted five cancer driver genes and found that KIT, ERBB2 and CEBPA are related to PI3K and RAS pathways." (PMID 32039169, 2019). "These investigators have also shown that HA constitutively regulates activation of several receptor tyrosine kinases, such as ErbB2, EGFR, PDGFR, IGFR and c-MET, which are known to be important in progression of various cancer types." (PMID 31294035, 2019). "ERBB2, CCND1, CCNE1 are well-characterized oncogenes present among our curated set of cancer driver databases." (PMID 31729402, 2019). "We performed a multiplex gene expression analysis using the Nanostring nCounter GX Human Cancer Reference kit for PT5 with a HR−/HER2+ subtype, which revealed high expression of HIF1A and HER2/ERBB2 (nCounts >500)." (PMID 31018595, 2019). "For example, the top 15 SGA-FIs (ranked according to the FDR p values of overlapping DEG sets) that share DEGs with PIK3CA include PTEN, CDH1, ERBB2, and GATA3, which are known cancer drivers, and their connections agree with existing knowledge." (PMID 31276486, 2019). "Moreover, to target cancer cells, NPs and μPs surfaces can be modified to increase the interaction with plasma membrane-specific markers like the transferrin receptor, the folate receptor, or the human epidermal growth factor receptor 2 (HER2, also known as ERBB2)." (PMID 30978948, 2019). "The CSmiR-Tar database identified erythroblastic oncogene B 2 (ERBB2) as a potential target gene of miR-301, across all cancer stages, with a binding site in the 5'UTR of ERBB2 which is structurally related to EGFR." (PMID 31756185, 2019). "In BC, amplification of receptor tyrosine kinases, such as ERBB2, EGFR, IGFR and FGFR1, and/or their upregulation contribute to cancer initiation and progression." (PMID 35582269, 2019). "The HER2/c-erbB-2, EGFR protein positive expression rate in cancer tissue and normal gastric tissue were compared." (PMID 33817143, 2019). "ERBB2 and FGFR1 are well-known receptor tyrosine kinases involved in the carcinogenesis of different types of cancers." (PMID 30850667, 2019). "EGFR, ERBB2 and members of the downstream PI3K/Akt and Ras pathways are potential therapeutic cancer targets, and they were all downregulated by the combination treatment." (PMID 30197755, 2018). "Erbb-2 belongs to the family of human epidermal growth factor receptor (HER) and plays a central role in many processes (especially in cancers) such as cell proliferation, survival and metastasis." (PMID 30072783, 2018).
cancer (continued). "In various types of cancer, including tumors of the head, neck, lung, and breast and colorectal tumors, the ErbB family of receptors (EGFR/HER1/ERBB1, HER2/neu/ERBB2, HER3/ERBB3, and HER4/ERBB4) is unregulated, producing an inappropriate cell stimulation." (PMID 30670929, 2018). "For example, eight patients across four cancer types were identified with low expression of EGFR when receiving cetuximab or lapatinib, or of ERBB2 when receiving erlotinib." (PMID 29783934, 2018). "Peaks involving important cancer genes such as CCND1, EGFR, ERBB2, FGFR1, AKT1, MYC, KRAS and CDKN2A/2B, which were confirmed in our data." (PMID 30131072, 2018). "Of those, we highlight four genes related to cancer development and progression (NOTCH2, ERBB2, MST1R, and RAF1) and two DNA repair genes (ERCC1 and SLX4)." (PMID 29868112, 2018). "When comparing fusion events with the remainder of the cancer cohort, fusions involving oncogenes such as EGFR, ERBB2, and RET had increased expression." (PMID 29617662, 2018). "Trastuzumab, an anti-ErbB2 antibody, and lapatinib, a small-molecule inhibitor of ErbB2/epidermal growth factor receptor (EGFR), are used for treatment of ErbB2-positive cancers." (PMID 30545388, 2018). "The data of ERBB2+ GC deposited in the cancer genome atlas (TCGA), gene expression omnibus (GEO), InBio MapTM, cancer cell line encyclopedia (CCLE), and cancer therapeutics response portal (CTRP) were analyzed." (PMID 30123134, 2018). "Particularly cancers that exhibit dependence upon specific oncogenic drivers, such as EGFR, ERBB2/HER2, ALK and mutant BRAF, are being treated with TKIs." (PMID 30544701, 2018). "There are 36 protein kinases in the Cancer Gene Census; seven of them (EGFR, ERBB2, BRAF, FLT3, PRKACA, LCK, and FGFR2) had enriched PTM/mutation domains in our study." (PMID 29695735, 2018). "This rise was due to alterations at a low percentage in genes with proven predictive value in the context of approved anti-cancer drugs (e.g., EGFR, BRAF, ERBB2, BRCA1, BRCA2, RET, ALK) in all cancer types." (PMID 29544535, 2018). "Secondly, FOXP3 represses several key target genes in cancer development, such as BRCA1, CD44, HER2/ERBB2, and SKP2, providing a strong link between FOXP3 and DNA repair system, as well as FOXP3 and cell cycle regulation." (PMID 30011797, 2018). "Correlations between LYL1 amplification and increased expression levels of cancer-related genes (MYC, CDK6, PRKACA, and ERBB2) are also observed." (PMID 29716549, 2018). "Of the non-T-cell related targets, the proteins currently most widely targeted are ERBB2 (HER2), EGFR, MS4A1 (CD20), CD22, PDCD1 (PD-1), MSLN (mesothelin), and ERBB3 (Her3), all for cancer indications." (PMID 28822103, 2018). "Abnormal activation of ERBB2 and PI3K/AKT cascade pathway is commonly related to tumorigenesis, drug resistance and carcinoma progression." (PMID 30126855, 2018). "It has been demonstrated that in cancer cells, activation of hepatocyte growth factor receptor (HGFR, also known as MET), human epidermal growth factor receptor 2 (HER2, also known as ERBB2), and tyrosine kinases stimulates cortactin phosphorylation." (PMID 29152154, 2017). "ErbB3/HER3 is a member of the epidermal growth factor receptor family of receptor tyrosine kinases comprising HER1 (EGFR), HER2 (ErbB2), HER3 (ErbB3) and HER4 (ErbB4) which play an important role in the development and progression of cancer." (PMID 28448604, 2017). "Several therapeutic agents are being used against the ERBB family members of ERBB2 and/or EGFR for treatment of human cancers in the clinic." (PMID 29321816, 2017). "Having identified ErbB2 as a protein carrier of the SLea antigen in ErbB2-overexpressing NCI-N87 cells, we aimed at dissecting the biosynthetic pathway of this cancer-relevant glycan epitope in this particular cell line, both in vitro and in silico." (PMID 29143776, 2017).
cancer (continued). "Cancer cell lines dependent on known receptor tyrosine kinases (such as EGFR, ERBB2, c-MET, and FLT3) were found to be sensitive to SHP2 depletion." (PMID 29371942, 2017). "In breast cancer, the post-transcriptional regulation of MUC4 is lost when cancer cells become unresponsive to TGF signals, most likely as a result of ErbB2 overexpression." (PMID 27829225, 2017). "Activation of ErbB2 downstream signaling pathways PI3K/AKT/mTOR and Ras/Raf/MEK/ERK contributes to trastuzumab resistance in ErbB2‐positive cancer cells." (PMID 28781955, 2017). "Dacomitinib (PF-00299804) is a tyrosine kinase inhibitor (TKI), which is predicted to only be effective in cancers where the targets of this drug (EGFR, ERBB2, ERBB4) are abnormally active." (PMID 28394918, 2017). "EGFR shares structural and functional properties with other members of the receptor family (HER2/ErbB2, HER3, HER4) all having roles in cancer development and drug resistance." (PMID 28186982, 2017). "However, the specific mechanism of miRNA in ERBB2-positive cancers is still unknown." (PMID 28160563, 2017). "HER-2 (ErbB-2, c-erbB2 or Her2/neu), a member of the HER-family, is directly involved in the pathogenesis and progression of several human cancers; as such, it is also often considered as a poor prognostic factor." (PMID 27542243, 2016). "Members of the human epidermal growth factor receptor (HER) family of receptor tyrosine kinases EGFR (HER1, ERBB1), HER2 (ERBB2), HER3 (ERBB3), and HER4 (ERBB4) are therapeutic targets in several cancers." (PMID 27610130, 2016). "Three cancer cells (black color, Calu-3, HCC827, and HCC358) showed higher ERBB2 and ERBB3 levels than other cell lines and were selected for further studies." (PMID 27626312, 2016). "With regard to cancer, the epithelial growth factor receptor (EGFR) has probably received the most interest, especially the family member HER2 (also known as erbB2)." (PMID 26771645, 2016). "Some important cancer genes, such as PIK3CA, BRCA1, BRCA2, and ERBB2, show a mixture of amplifications and deletions." (PMID 27556158, 2016). "The use of antibodies is an established cancer therapy approach, with antibodies targeting EGFR, ERBB2, and VEGF (vascular endothelial growth factor) demonstrating effectiveness." (PMID 26760963, 2016). "Their results point to a subtype of carcinomas characterized by ERBB2 RNA and erbB-2 protein underexpression." (PMID 29056725, 2016). "Other proteins that are dysregulated in cancer are also affected by AIMs, including: JNK; JAK1 and STAT3; Her2 (ERBB2); death receptor 5 (TNFRSF10B); and cFLIP (CFLAR)." (PMID 25897966, 2015). "Several genes (for example, RIPK2, EFNA4 and TMEM9B) showed differential expression in subtypes associated with high proliferation, such as IntClust 5 (predominantly HER2/ERBB2-amplified cancers) and IntClust 10 (predominantly basal expression type cancers)." (PMID 25572802, 2015). "We tested combinations of the EGFR/ERBB2 inhibitor neratinib with the cell cycle inhibitors (BI-2536, GSK-1070916 and paclitaxel or docetaxel) in the MYC-amplified cancer cell line NCI-H82." (PMID 26018524, 2015). "HER family pathway activation (p-erbB2, p-EGFR, p-HER3) was common in the primary and MBC samples, with downstream activation of p-mTOR and p-STAT3 seen in several patients’ cancers." (PMID 25871911, 2015). "Interestingly, hypoxic ERBB2-expressing cells in 3D culture were hypersensitive to trametinib treatment alone compared to normoxic cells, suggesting that hypoxic cancer cells may be more dependent on the MEK-ERK pathway for cell survival and thus more sensitive to MEK inhibitors." (PMID 25596742, 2015). "In cancer therapy, drugs acting on the HER2 (erb-b2 receptor tyrosine kinase 2) and EGFR (epidermal growth factor receptor) pathways have shown this type of drug evasion effects." (PMID 26047322, 2015).
cancer (continued). "HRG plays an important role in human cancer through its conventional paracrine or autocrine ability to bind and activate the HER-2/-3/-4 (erbB-2/-3/-4) tyrosine-kinase cell surface receptors." (PMID 26327598, 2015). "We further added to the complement of known RAS-activating mutations in observing mutations in BRAF (two MC), as well as previously unreported potentially RAS-activating alterations in FGFR2, ERBB2, and STK11, each affecting a single carcinoma." (PMID 25986173, 2015). "Among the 73 cancer amplified genes were a number of established drug targets, such as EGFR, ERBB2 and KIT." (PMID 24874471, 2014). "ERBB2 is a member of the epidermal growth factor receptor (EGFR/ErbB) family, and usually over expressed in many kind of cancer cells and promoting cell proliferation." (PMID 25479352, 2014). "ERBB3 limits the impact of exclusively targeting ERBB1/EGFR or ERBB2/HER2 and provides a route for acquired resistance to anti-cancer drugs that inhibit ErbBs." (PMID 25248370, 2014). "The erbB receptors, including the epidermal growth factor receptor (EGFR), erbB2 (also known as HER2/neu), erbB3 (or HER3), and erbB4 (or HER4), are often aberrantly activated in a wide variety of human cancers." (PMID 24886126, 2014). "In contrast to EGFR and ERBB2, the potency of ERBB3 as a therapeutic target in cancer has only recently been recognized." (PMID 24970817, 2014). "Gene amplification in cancer cells provides a means for overexpression of cancer-promoting driver genes, such as EGFR and ERBB2 on chromosomes 7 and 17, respectively." (PMID 24874471, 2014). "In summary, our studies define putative and novel resistance mechanisms to lapatinib in ErbB2-positive cancers and identify irreversible EGFR/ErbB2 inhibitors as capable of overcoming such resistance." (PMID 25238247, 2014). "Not surprisingly, the overexpression of ERBB3 has been frequently detected in many types of human cancers, and accumulating evidence strongly suggests that ERBB3 plays a crucial role in cancers driven by EGFR and ERBB2." (PMID 24970817, 2014). "While several therapeutic agents against erbB2 and/or EGFR have been used in the treatment of human cancers with efficacy, there has been relatively less emphasis on erbB3 as a molecular target." (PMID 24886126, 2014). "As lapatinib and imatinib/nilotinib are FDA-approved for use in various cancer types, our data suggest a clinical opportunity for the personalization of therapy for the subset of Ph+ALL patients that exhibit ErbB2 expression." (PMID 23936456, 2013). "In the pathways in cancer, TGFA and ERBB2 are both important regulators of normal mammary gland physiology, and aberrations in their signaling have been associated with breast tumorigenesis." (PMID 23369492, 2013). "Altogether, our in vitro and in vivo data indicate that the ERBB2 gene is a novel MBP-1 target, and immunohistochemistry analysis of primary tumors suggests that the concomitant high expression of MBP-1 and HDAC1 may be considered a diagnostic marker of cancer progression for breast IDC." (PMID 23421821, 2013). "Since active ErbB2 promotes a myriad of survival and proliferative signaling pathways in cancer cells, the pan-ErbB TKI canertinib was used to block ErbB2 phosphorylation." (PMID 23936456, 2013). "ErbB2 or HER2/neu, as well as ROR1 are members of the type I RTKs contributing to the malignant phenotype of several human cancers." (PMID 24205204, 2013). "In contrast, CB2 immunoreactivity was documented in 72% of human breast tissues, and is present in 91% of ErbB2-positive cancer tissues (in contrast to CB1 receptor), suggesting a relationship between CB1 receptor and the ErbB2-positive cancer cell phenotype." (PMID 24369462, 2013).
cancer (continued). "Gene amplification of the ESR1 gene, encoding the ER, has been the focus of recently published studies, as gene amplification is the major mechanism behind the cancer-related changes of many oncogenes, including ERBB2 (HER2)." (PMID 23923010, 2013). "Indeed, ErbB2 blockade with certain monoclonal antibody inhibitors can lead to cardiac toxicities in cancer patients and thus, use of delivery systems or other targeting strategies that allow selective blockade of erbB2 in the vasculature may be required for clinical applications." (PMID 23826343, 2013). "The EGF receptor family consists of four members: ErbB1/EGFR/HER1, ErbB2/HER2/Neu, ErbB3/HER-3 and ErbB4/HER-4 that are important for cancer development." (PMID 23173670, 2012). "Overall, the hazard ratios of cancer progression were 4.611 (95% CI: 2.5–8.4) for EGFR and 1.067 (95% CI: 0.59–1.97) and ErbB2 overexpression." (PMID 22991510, 2012). "A number of cancer-related genes are located in these two RARs: NUPR1, MVP, MAPK3, FUS, and PYCARD are located in RAR-G12 while ERBB2, GRB7, and PPP1R1B are located in RAR-G13." (PMID 22938721, 2012). "While this is interesting, and perhaps suggests the expression of a different PADI family member in this basal cell line, we have focused on PADI2 expressing cancers for this study, which are predominantly luminal and HER2/ERBB2 expressing." (PMID 23110523, 2012). "ERBB3 is a critical activator of PI3K signaling in EGFR (ERBB1)-, ERBB2 (HER2)-, and MET-addicted cancers." (PMID 23691449, 2012). "Overall, the hazard ratios of cancer death were 3.044 (95% CI: 1.6–5.9) for EGFR and 1.090 (95% CI: 1.0–1.2) for ErbB2 overexpression." (PMID 22991510, 2012). "The epithelial growth factor receptor (EGFR) family consists of four members, EGFR (HER1), ErbB2 (HER2), ErbB3 (HER3), and ErbB4 (HER4), and has been shown to play an important role in metastasis and tumorigenesis in many types of human cancers." (PMID 22479527, 2012). "Several known copy number alteration drivers in cancers include receptor tyrosine kinases such as EGFR, FGFR, and ERBB2, which are targets for drugs therapy." (PMID 23078675, 2012). "At day 10, the strongest suppression of SK-BR-3 growth on the Test Cancer BioChip was observed using siRNAs for ACTB, PIK3CA, and ERBB2." (PMID 23049944, 2012). "Most of these regions have been validated to encompass or closely near to cancer related genes such as MDM2, MYC, EGFR, ERBB2, CCND1, ARNT." (PMID 23285074, 2012). "Thus, inhibition of erbB2 activity might represent a new avenue for successful inhibition of potential metastasis formation, and represents a new therapeutic target for future personalized cancer therapies." (PMID 21481261, 2011). "Two recent studies demonstrate interesting relationships between cancer oncogenes (KRAS, BRAF and ErbB2), regulation of glucose transport and cell survival under conditions of stress." (PMID 21826239, 2011). "The antiproliferative effects of AST1306 were then evaluated in a panel of human cancer cell lines with varying levels of EGFR and ErbB2 expression." (PMID 21789172, 2011). "We next evaluated the targets inhibition of AST1306 in human cancer cells that overexpress EGFR and/or ErbB2." (PMID 21789172, 2011). "Overexpression of Her2/ErbB2/Neu, a member of the epidermal growth factor receptor (EGFR)-family tyrosine kinases, in malignant tumors is often correlated with recurrent distant metastasis." (PMID 21966491, 2011). "The receptor tyrosine kinases (RTKs) and drug targets EGFR, ERBB2 and MET were each amplified (log2 > 0.6) and overexpressed at the RNA level in one cancer sample." (PMID 21781349, 2011). "While IHC shows erbB2 receptor overexpression in cancer specimens, FISH confirms erbB2 gene amplification." (PMID 21876697, 2011).